SALL3 (spalt like transcription factor 3)
Description:
Probable transcription factor.
Synonyms: ZNF796
Tractability: PROTAC: ubiquitination databases record sites on it.
Gene: Protein-coding gene on chromosome 18 (78,979,818 to 79,002,677, forward strand). Ensembl gene ENSG00000256463.
Subcellular location: Nucleus
Gene Ontology:
Molecular function: DNA-binding transcription factor activity, RNA polymerase II-specific
Biological process: regulation of transcription by RNA polymerase II; cell differentiation; limb morphogenesis; olfactory bulb development; regulation of signal transduction
Cellular component: nucleus
Genetic constraint (gnomAD): Loss-of-function variants: 24 observed, 44.79 expected, observed/expected ratio (o/e) 0.54, 90% interval 0.39 to 0.75. The synonymous counts are far from expectation, so gnomAD's model fits this gene poorly and the ratio says little. Missense variants: 1,893 observed, 1,541.5 expected, observed/expected ratio (o/e) 1.23, 90% interval 1.18 to 1.28. Synonymous variants: 1,009 observed, 721.34 expected, observed/expected ratio (o/e) 1.4, 90% interval 1.33 to 1.47.
Homologues: Orthologues: chimpanzee SALL3 (97% identical), macaque SALL3 (92% identical), mouse Sall3 (85% identical), rat Sall3 (84% identical), dog SALL3 (84% identical), pig SALL3 (81% identical), rabbit SALL3 (78% identical), guinea pig SALL3 (76% identical), tropical clawed frog sall3 (74% identical), zebrafish sall3a (58% identical). Paralogues in human: SALL1 (52% identical), SALL4 (37% identical), SALL2 (24% identical), HIVEP1 (15% identical), HIVEP3 (15% identical), ZNF536 (14% identical), HIVEP2 (13% identical), BCL11B (12% identical), ZNF516 (11% identical), BCL11A (11% identical), ZNF831 (10% identical), RREB1 (10% identical), and 2 more.
Diseases named in the same sentence as SALL3 in open-access papers:
SALL3 is named in the same sentence as 25 diseases in open-access papers, as found by Europe PMC text mining. Sharing a sentence is not in itself a finding about the gene and the disease. The quoted sentences say what the papers report.
bladder cancer (4 papers, 2014 to 2019). "Accordingly, methylation profiling of urine sediments, to detect the top four frequently methylated genes, namely SALL3, CFTR, ABCC6, and HPP1, together can detect bladder cancer with 82.6% sensitivity and 100% specificity." (PMID 30901947, 2019). "To analyze samples negative for BCL2 methylation, we expanded the MethyLight-based analysis by six additional promoter CpG islands previously reported to be frequently hypermethylated in bladder cancer, including CCNA1, EOMES, HOXA9, POU4F2, SALL3 and VIM2." (PMID 24732047, 2014). "Furthermore, recurrent bladder cancer patients were found to display higher proportions of SALL3 DNA methylation compared to that in non-recurrent bladder cancer patients." (PMID 30901947, 2019).
cervical cancer (4 papers, 2015 to 2019). A primary or metastatic malignant neoplasm involving the cervix. "Aberrant hypermethylation of SALL3 is also positively associated with HPV infection in cervical cancer." (PMID 30901947, 2019). "High-risk HPV infection as an etiology of cervical cancer participated in SALL3 methylation." (PMID 26697877, 2015). "The methylation rates of IFN-γ, FHIT, MGMT, CDKN2A, SALL3, and gene promoters were significantly higher in cervical cancer tissues than those in CIN and normal cervical tissues, which are related to the progression of cervical oncogenesis." (PMID 29850477, 2018). "HPV infection is also associated with hypermethylation of the promoter region of SALL3, DLX4, and SIM1 genes, which should be a significant progression marker for HPV infection in cervical cancer." (PMID 29850477, 2018). "Methylation of the SALL3 promoter was observed in 15 of 23 (65.21%) cervical cancer tissue samples, 15 of 23 (65.21%) matched pericarcinomatous tissue samples and 5 of 17 (29.41%) normal cervical tissue samples (p<0.05)." (PMID 26697877, 2015). "Then, MTT assay showed that after treated with 5-Aza, the cell viability and proliferation of SiHa and HeLa significantly weakened which illustrated a cancer-inhibiting function of SALL3 in cervical cancer cells." (PMID 26697877, 2015). "We detected the expression of SALL3 mRNA in the 23 cervical cancer tissues, 23 matched pericarcinomatous tissues and 17 normal cervical tissues by real-time Q-PCR." (PMID 26697877, 2015). "We suggest that DNA methylation of SALL3 inhibits its role as a tumor suppressor and contributes to the carcinogenesis of cervical cancer." (PMID 26697877, 2015). "In conclusion, our research first demonstrated that the promoter of SALL3 was of hypermethylation, and due to this mechanism down-regulated the mRNA expression and accelerated cell growth in cervical cancer tissues and cell lines." (PMID 26697877, 2015). "Given that high-risk HPV infection is involved in the etiology of cervical cancer, we further explored the relationship between HPV infection and hypermethylation of the SALL3 promoter region in cervical cancer." (PMID 26697877, 2015). "SALL3 mRNA expression was significantly lower in cervical cancer and pericarcinomatous tissues compared with normal cervical tissues (p<0.05)." (PMID 26697877, 2015). "In our study, we have explored the feasibility of detecting hypermethylated SALL3 in promoter regions as a screening method for cervical cancer." (PMID 26697877, 2015). "The relationship between HPV infection and hypermethylation of SALL3 in cervical cancer." (PMID 26697877, 2015). "Methylation status of SALL3 in cervical cancer, pericarcinomatous tissues and normal cervix." (PMID 26697877, 2015). "To further confirm the methylation status of the promoter region of SALL3 in cervical cancer tissues, we performed MSP in 23 cervical cancer tissues, 23 matched pericarcinomatous tissues and 17 normal cervical tissues." (PMID 26697877, 2015). "To identify the methylation status of this region in cervical cancer cell lines, we used methylation-specific PCR (MSP) to determine the SALL3 promoter methylation status in SiHa, C33A and HeLa cells." (PMID 26697877, 2015). "However, whether SALL3 is involved in the carcinogenesis of cervical cancer remains unknown." (PMID 26697877, 2015). "In our current study, we demonstrated that the promoter region of SALL3 is hypermethylated and, together with HPV infection, is involved in cervical cancer; additionally, the expression level of SALL3 mRNA was down-regulated." (PMID 26697877, 2015). "The aberrant hypermethylation of SALL3 together with HPV involvement inactivated its function as a tumor suppressor and contributed to carcinogenesis in cervical cancer." (PMID 26697877, 2015).
cervical cancer (continued). "This study aimed to investigate the methylation status of the promoter region of spalt-like transcription factor 3 (SALL3) and the expression of SALL3 in cervical cancer to explore the function of this gene in cervical cancer carcinogenesis." (PMID 26697877, 2015). "HPV infection was positively associated with hypermethylation of the SALL3 promoter, and SALL3 mRNA level was lower in HPV-positive as compared to -negative cervical cancer tissues." (PMID 28616099, 2017). "In cervical cancer cell lines SiHa and HeLa, of which were both HPV positive cell lines, were methylated in SALL3 promoter regions but in C33A, an HPV negative cell line, SALL3 was unmethylated in the promoter region." (PMID 26697877, 2015).
hepatocellular carcinoma (4 papers, 2010 to 2019). A malignant tumor that arises from hepatocytes. "SALL3 hypermethylation has been reported in several cancers, including in cervical and breast cancers and hepatocellular carcinoma." (PMID 28616099, 2017). "SALL3 is silenced by DNA methylation and the protein directly interacts with DNMT3A in human hepatocellular carcinoma; SALL3 inactivation by DNA methylation was found to accelerate aberrant DNA methylation." (PMID 28616099, 2017).
thyroid cancer (2 papers, 2010 to 2021). "For instance, we failed to explore the role of the 5 feature genes (BMP8A, ADARB2, SALL3, PPBP, and SCN1A) in onset and progression of thyroid carcinoma by molecular experiments, cell experiments, or animal experiments." (PMID 34697553, 2021).
cleft lip (1 paper, 2022). Congenital defect in the upper lip where the maxillary prominence fails to merge with the merged medial nasal prominences. "The region related to cleft lip and cleft palate is 18q22.3q23, and the possible related pathogenic genes are SALL3 and TSHZ1." (PMID 36123715, 2022).
endometrial cancer (1 paper, 2024). Primary or metastatic malignant neoplasm involving the endometrium (mucous membrane that lines the endometrial cavity). "The deletion-only model identified a total of 59 gene loci associated (p < 0.01) with endometrial cancer, including two loci (SLCO1B3 and SALL3) that met the Bonferroni genome-wide threshold of significance." (PMID 39495297, 2024).
head and neck squamous cell carcinoma (1 paper, 2021). A squamous cell carcinoma that arises from any of the following anatomic sites: lip and oral cavity, nasal cavity, paranasal sinuses, pharynx, larynx, and salivary glands. "Several studies indicate that the hypermethylation of SALL1 and SALL3 promoters correlates with poor outcomes and recurrence in head and neck squamous cell carcinoma (HNSCC)." (PMID 34944911, 2021).
Hypertension (1 paper, 2016). The presence of chronic increased pressure in the systemic arterial system. "Of those, 28 genes had more than 5 var-HpaII sites, and several of those have been reported the association with PE (PTPRN2, KCNMA1, and NFATC1), hypertension (SDK1), and placental development (SALL3)." (PMID 27293492, 2016).
lymph node metastasis (1 paper, 2017). "SALL3 methylation status in patients with T1 and T2, without lymph node metastasis, or Stage I and II tumors was not related to outcome." (PMID 28616099, 2017). "Patients with T3 and T4, lymph node metastasis, and Stage III and IV tumors had decreased DFS as compared to those without SALL3 methylation (P = 0.024, P = 0.029, and P = 0.008, respectively)." (PMID 28616099, 2017).
prostate carcinoma (1 paper, 2018). A carcinoma that arises from epithelial cells of the prostate gland. "Further, SNPs in the SALL3 region have also been associated with prostate cancer, which may suggest additional links between 2D:4D ratio and testosterone." (PMID 29659830, 2018).
spine chordoma (1 paper, 2022). "As for transcriptome biomarkers, LMX1A is dominant in skull base chordoma, and SALL3 is unique to spine chordoma." (PMID 36185236, 2022).
thymoma (1 paper, 2022). A neoplasm arising from the epithelial cells of the thymus. "Bisulfite pyrosequencing in 46 TEN and 20 paired thymus tissues revealed higher promoter methylation of G protein subunit gamma 4 (GNG4), growth hormone secretagogue receptor (GHSR), homeobox D9 (HOXD9) and spalt like transcription factor 3 (SALL3) in TC than in thymoma." (PMID 35409405, 2022).
tumor (12 papers, 2010 to 2025). "We found that hypermethylation of CpG islands in the SALL3 promoter was independently associated with aggressive tumor behavior, suggesting that SALL3 acts as a tumor suppressor gene and can serve as a prognostic biomarker in HNSCC." (PMID 28616099, 2017). "SALL3 tumor suppressor function was associated with CpG island methylation in HCC." (PMID 34944911, 2021). "Additionally, Zhang and collaborators identified SALL1 and SALL3 as part of a high-risk group of genes differentially expressed within a vast number of genes whose methylation status also differed when comparing tumor and adjacent normal tissue." (PMID 34944911, 2021). "Moreover, transcriptional inactivation of SALL3 was associated with aberrant methylation of other tumor-related genes and TET1, TET2, and DNMT3A levels in HNSCC." (PMID 28616099, 2017). "Furthermore, transcriptional inactivation of Sal-like protein 3 (SALL3) was found to be associated with aberrant methylation of other tumor-related genes and ten-eleven translocation (TET) family genes, as well as DNA methyltransferase 3 alpha (DNMT3A) levels, in HNSCC." (PMID 30901947, 2019). "Another example is that the promoter of spalt-like transcription factor 3 (SALL3) gene was hyper-methylated in HCC tumor tissues in this study." (PMID 37936230, 2023). "In oral squamous cell carcinoma (OSCC), SALL2 promoter hypermethylation positively correlates with SALL1 and SALL3 promoter methylation status and aggressive tumor behavior." (PMID 34944911, 2021). "Given the complex regulation of gene expression, several key upregulated genes were found, including GATA4, SALL3, IL33, SOX10, and SCG3/SHC4, while the downregulation of keratin genes suggests a loss of epithelial differentiation, contributing to aggressive tumor behavior." (PMID 40647405, 2025). "Other interesting candidates were NOX5, whose activation was demonstrated to inhibit cancer stem cell formation through ROS generation, and SALL3, which was reported to directly inhibit DNMT3A activity and consequently cause DNA hypomethylation and activation of tumor suppressor genes." (PMID 34439480, 2021). "We suggest that methylation-induced silencing of SALL3 facilitates methylation of tumor-related genes, leading to de novo DNA methylation of DNMT3s and ten-eleven translocation (TET) family genes that potentiates enzymatic conversion of 5-methylcytosine (5mC) to 5-hydroxymethylcytosine (5hmC)." (PMID 28616099, 2017). "Hypermethylation of tumor-related genes was higher among patients with SALL3 methylation than among those without methylation (P < 0.001)." (PMID 28616099, 2017). "To test this hypothesis, we investigated the methylation status of SALL3 in 165 HNSCC cases at diagnosis and during follow-up to assess its clinical significance and potential as a prognostic biomarker for tumor recurrence and patient survival." (PMID 28616099, 2017). "Indeed, SALL3 promoter methylation was increased in tumor tissue as compared to that in noncancerous mucosae from the same patient." (PMID 28616099, 2017). "In humans, SALL3 is not considered a significant prognostic marker, and its overexpression in COM could suggest a role in tumor progression, although further research is needed to confirm this hypothesis." (PMID 40647405, 2025).
cancer (8 papers, 2010 to 2024). A tumor composed of atypical neoplastic, often pleomorphic cells that invade other tissues. "SALL1, SALL2, and SALL3 hypermethylation are associated with bad prognosis in several cancers, and the epigenetic silencing of SALL2 confers tamoxifen resistance in breast cancer." (PMID 34944911, 2021). "The hypermethylation of the SALL3 promoter was described in different HPV-related cancer cell lines and tissues such as cervical cancer and HNSCC." (PMID 34944911, 2021). "Concerning the role of SALL3 in cancer development and progression, the available information is still scarce, but we will discuss recent studies on SALL3 by cancer subtype in the next section." (PMID 34944911, 2021). "In tissue samples, the Q-PCR results suggested that mRNA expression of SALL3 was higher in cancer and pericarcinomatous tissues than in normal cervix tissues(p<0.05), which shared the similar idea with previous studies." (PMID 26697877, 2015). "The SALL3 gene might thus play a role in the tumorigenesis and could serve as an important biomarker for human cancers." (PMID 30901947, 2019). "HDIs, TSA, depsipeptide and sodium butyrate, were shown to enhance the expression of genes such as CDKN2A, CDKN1A, SALL3, RARb2, TERT and GATA4 in human cancer cell lines by active DNA demethylation of their respective promoters." (PMID 28077797, 2017). "Histone Deacetylase Inhibitors (HDIs) have been shown to activate silenced genes including CDKN1A, CDKN2A,SALL3, RARb2, TERT and GATA4, in the human cancer cells by active DNA demethylation of their respective promoters." (PMID 28077797, 2017). "In all cancer cell lines with reduced SALL3 expression, the NMV of SALL3 was higher than that in normal cell lines; moreover, the absence of SALL3 expression was associated with hypermethylation." (PMID 28616099, 2017).
infection (1 paper, 2015). The state of being infected such as from the introduction of a foreign agent such as serum, vaccine, antigenic substance or organism. "Taken these together, the infection of HPV might participate in the mechanism of SALL3 methylation-related carcinogenesis." (PMID 26697877, 2015).
SALL3 also shares sentences with these, for which no sentence is quoted: breast carcinoma (2 papers); lung carcinoma (2); Burkitt lymphoma tumors (1); colon cancer (1); colorectal cancer (1); germ cell tumors of the (1); head and neck cancer (1); kidney cancer (1); ovarian carcinoma (1); yolk sac tumor (1).